FGF21 (fibroblast growth factor 21)
Diseases named in the same sentence as FGF21 in open-access papers (continued):
Sharing a sentence is not in itself a finding about the gene and the disease.
atherosclerosis (continued). "FGF21 is an independent predictor of and risk marker for atherosclerosis." (PMID 36006939, 2022). "Increased FGF21 levels have been reported to be associated with atherosclerosis and CAD." (PMID 35307922, 2022). "Deficiency of FGF21 aggravates the development of atherosclerosis." (PMID 36006939, 2022). "The mechanisms of atherosclerosis prevention induced by FGF21 may be associated with suppression of endoplasmic reticulum stress-mediated apoptosis." (PMID 34513950, 2021). "Moreover, high serum levels of FGF-21 in DM patients were shown to be correlated with subclinical atherosclerosis and a relatively high risk of CV events in short- and long-term studies." (PMID 33810243, 2021). "However, despite adjustment for systolic blood pressure and pulse pressure, FGF21 remained independently associated with subclinical atherosclerosis in females, thus suggesting other possible interacting factors as well." (PMID 33996935, 2021). "This study can also be of great help to follow-up studies aiming to evaluate the effect of FGF21 on atherosclerosis, the associated mechanisms, and the effects of combination with other novel antidiabetic medications, such as GLP-1 analogues and SGLT-2 inhibitors." (PMID 32957703, 2020). "However, several studies have shown that increased levels of circulating FGF-21 are associated with the presence of atherosclerosis, although there are contradictory results." (PMID 33081064, 2020). "Fibroblast growth factor 21 (FGF21) is a myokine, which may be important in detecting subclinical atherosclerosis, which may be a pathogenetic cause of stroke." (PMID 28373915, 2017). "Strong evidence showed that the development of CVDs including atherosclerosis, coronary heart disease, myocardial ischemia, cardiac hypertrophy, and diabetic cardiomyopathy is associated with serum FGF21 levels increase which was regarded as a compensatory response to induced cardiac protection." (PMID 27247947, 2016). "Therefore, further studies will be needed to elucidate the impact of NAFLD on the association of FGF21 and subclinical atherosclerosis." (PMID 26047614, 2015). "Therefore, whether elevated FGF21 expression is due to FGF21 resistance or induced to protect the heart from atherosclerosis caused by an atherogenic diet and chronic BaP exposure needs further investigation." (PMID 39108652, 2024). "In addition, FGF21 may reduce the risk of atherosclerosis due to lowering inflammation, regulating of lipid metabolism and its effect on adiponectin expression." (PMID 36457562, 2022). "Therefore, FGF21 has a stronger association with atherosclerosis than arteriosclerosis." (PMID 34513950, 2021). "Clinical studies indicated that serum FGF21 changes were positively associated with the development of atherosclerosis, coronary heart disease, myocardial ischemia, cardiac hypertrophy, and diabetic cardiomyopathy, which implies that upregulated endogenous FGF21 may improve CVDs." (PMID 27247947, 2016). "Some myokines such as fibroblast growth factor 21, musclin, and apelin have a salutary effect on the cardiovascular system, which is related to protection against atherosclerosis and blood pressure control." (PMID 40594910, 2025). "Fibroblast growth factor 21 (FGF21) further protects against atherosclerosis by stimulating adiponectin expression in adipose tissue and inhibiting cholesterol synthesis in the liver." (PMID 41302972, 2025). "The antagonistic effect of FGF21 on atherosclerosis is attributed to its ability to induce adiponectin secretion in adipocytes and suppress hepatic cholesterol biosynthesis." (PMID 41234361, 2025). "Recent studies have shown that FGF21 exerts protective effects against atherosclerosis via multiple mechanisms." (PMID 40765997, 2025). "The correlation analysis showed a positive correlation between FGF21 and the presence of atherosclerosis (95% CI r = 0.0042 to 0.4607, p = 0.046)." (PMID 40299570, 2025).
atherosclerosis (continued). "For example, by binding to its receptors, β-klotho (KLB) and FGF receptor 1 (FGFR1), FGF21 down-regulates hepatic sterol regulatory element binding protein-2 to inhibit cholesterol biosynthesis and induce adiponectin to inhibit atherosclerosis." (PMID 40765997, 2025). "Regular physical exercise elevates FGF21 levels to regulate the immune response in atherosclerosis, thereby reducing plaque formation." (PMID 40861271, 2025). "FGF21 ameliorates atherosclerosis by inhibiting hepatic SREBP2 expression and promoting adipocyte-derived adiponectin production." (PMID 41234361, 2025). "Although the involvement of FGF21 in atherosclerosis has been established through genetic knockout mouse studies, its correlation with carotid intima-media thickness (IMT) in humans is not well defined." (PMID 40559404, 2025). "In a rat model of atherosclerosis, FGF-21 increased SOD levels, glutathione levels, and decreased malondialdehyde levels." (PMID 39558976, 2024). "Several reports have found that serum levels of FGF21 were increased in subjects with non-alcoholic fatty liver disease, hyperlipidemia, hypertension, and atherosclerosis." (PMID 37864659, 2024). "Surely, highlighting the relationship between FGF21 and BaP will open a window for further understanding of the mechanism of BaP in cardiovascular disease and atherosclerosis." (PMID 39108652, 2024). "FGF21 inhibited atherosclerosis through mitigating Fas-mediated apoptosis in ApoE-/- mice, and in vitro studies have found that FGF21 inhibited apoptosis and prevented atherosclerosis progression in HUVEC through the Fas/FADD mechanism." (PMID 39558976, 2024). "Our findings revealed that BaP increases the expression of endogenous FGF21 in treated animals as a compensatory response to protect the heart from atherosclerosis induced by BaP and AtD." (PMID 39108652, 2024). "In some clinical studies, FGF21 is considered a biomarker for predicting the presence of atherosclerosis and cardiovascular events 41-47." (PMID 36594101, 2023). "Some outstanding achievements on the research of FGF21 in hypertension (HP) and atherosclerosis (AS) have been obtained." (PMID 38057786, 2023). "In conclusion, FGF21 can modulate proatherogenic cellular events, including vascular endothelial cells, macrophages, and vascular smooth muscle cells, to protect against atherosclerosis and CAD." (PMID 36594101, 2023). "In vitro experiments proved that FGF21 can inhibit macrophage-derived foam cell formation to improve atherosclerosis." (PMID 36594101, 2023). "Recent studies have shown that FGF21 can also act as a predictor of atherosclerosis by inhibiting mitochondrial fragmentation to reduce ROS production, and ultimately reducing NLRP3-mediated cellular death in endothelial cells to resist atherosclerosis." (PMID 37822930, 2023). "Several studies have assessed the association of FGF21 with CAD, subclinical atherosclerosis, and AF." (PMID 36028609, 2023). "FGF21 has been shown to play a protective role in various cardiovascular diseases including MI, atherosclerosis, and diabetic cardiomyopathy in different studies, and FGF21 knockout mice tend to present pathological phenotypes." (PMID 37416922, 2023). "Studies showed that FGF-21 exerts protective effects against the development of atherosclerosis through the modulation of interactions between the adipose tissue, liver, and blood vessels, reducing vascular inflammation and oxidative stress." (PMID 35186330, 2022). "Studies have shown that the downstream signal passage of FGF21 in patients with atherosclerosis is damaged, resulting in FGF21 resistance." (PMID 36006939, 2022). "Our previous studies indicated that FGF21 is significantly increased in both mouse models of atherosclerosis and patients with coronary heart disease." (PMID 35463746, 2022).
atherosclerosis (continued). "Fibroblast growth factor 21 (FGF21), a known risk factor for atherosclerosis, is readily regulated by exercise, and it can inhibit NOD-like receptor protein 3 (NLRP3)-mediated pyroptosis." (PMID 36006939, 2022). "Paradoxically, the serum FGF21 level is elevated in patients with atherosclerosis and is one of the most sensitive predictors of atherosclerosis." (PMID 36006939, 2022). "This shows that in metabolic diseases such as atherosclerosis, the downstream signaling pathway of FGF21 is disrupted and a state of FGF21 resistance appears, leading to an increase in the concentration of FGF21 to compensate." (PMID 36006939, 2022). "Herein, FGF21-medieted PVAT activation is indicated to be an effective method for the treatment of DM-related atherosclerosis." (PMID 34349728, 2021). "FGF-21 blood levels were higher in mouse models of obesity-related diseases, including chronic hyperglycemia, nonalcoholic fatty liver disease, and atherosclerosis." (PMID 34659937, 2021). "An interaction test assessing interaction by sex on the relationship between subclinical atherosclerosis and FGF21 showed a significant interaction with sex (Pinteraction = 0.033)." (PMID 33996935, 2021). "Previous studies have shown that FGF21 has inhibited atherosclerosis, vascular calcification, and cardiomyocyte apoptosis by reducing ER stress." (PMID 34777697, 2021). "We explore differences in intermediary mechanisms, in terms of hypertension, lipids, and inflammation, between FGF21 and atherosclerosis." (PMID 33996935, 2021). "Several animal studies have also revealed that FGF21 deficiency aggravates the severity of diabetic nephropathy and atherosclerosis in mice, suggesting the potential organ protective role of FGF21 in chronic metabolic diseases." (PMID 34773993, 2021). "It is reported that elevated serum level of FGF21 was related to atherosclerosis in subjects with DM, suggesting FGF21 resistance and/or a compensatory mechanism in response to DM." (PMID 34349728, 2021). "In experimental models of atherosclerosis, FGF21 has been demonstrated to exert anti-atherosclerotic effects by a reduction of NLRP3 related pryoptosis of endothelial cells." (PMID 33846498, 2021). "Administration of FGF21 showed anti-atherosclerotic effects in atherosclerosis-prone mice and exerted beneficial effects on critical atherosclerosis pathways." (PMID 32957703, 2020). "One study uncovered the protective effects of FGF21 against atherosclerosis via the induction of adiponectin in adipose tissue, and reduction of hypercholesterolemia by suppression of hepatic SREBP-2 levels." (PMID 32957703, 2020). "Also, further prospective studies are needed to clarify whether FGF21 can be used as a predictive biomarker to identify individuals at high risk of atherosclerosis in atherosclerosis‐associated diseases and whether FGF21 therapy can reduce the risk of atherosclerosis in these diseases." (PMID 32227589, 2020). "In rats with atherosclerosis, FGF-21 decreases inflammation by increasing the signalling of nuclear factor erythroid 2-related factor 2 (Nrf2)-antioxidant response elements (ARE) and by reducing the expression of NF-κB." (PMID 33081064, 2020). "Here, we investigated the effects of FGF21 on cardiometabolic parameters in atherosclerosis-prone ApoE−/− mice." (PMID 32957703, 2020). "A study using ApoE−/− mice reported that the administration of FGF21 alleviated atherosclerosis by ameliorating Fas-mediated apoptosis." (PMID 32957703, 2020). "Several studies have shown a protective role of FGF-21 against atherosclerosis via the regulation of different signalling pathways involved in inflammation, oxidative stress, cholesterol synthesis, and cell viability." (PMID 33081064, 2020). "In this study, FGF21 analogue therapy was effective against the development of atherosclerosis in addition to its known glucose-lowering property." (PMID 32957703, 2020).
atherosclerosis (continued). "This study demonstrated that treatment with FGF21 reduced atheromatous plaque formation in the aortic arch and valves, using an atherosclerosis-prone mouse model." (PMID 32957703, 2020). "Due to its anti‐oxidative, anti‐inflammatory, lipid‐lowering and adiponectin‐increasing effects, FGF21 directly or indirectly represses signalling pathways that lead to atherosclerosis." (PMID 32227589, 2020). "It has also been reported that FGF21 protects against atherosclerosis in a mouse model of atherosclerosis." (PMID 32584895, 2020). "In this study, we report that DCA systematically ameliorates atherosclerosis via FGF21-mediated enhanced energy expenditure in an AMPK-dependent manner, which was confirmed by increased glucose uptake associated with enhanced energy expenditure." (PMID 31570705, 2019). "Taken together, the results suggest that enhanced glucose oxidation by DCA protects against atherosclerosis by inducing hepatic FGF21 expression and BAT activation, resulting in augmented energy expenditure for heat generation." (PMID 31570705, 2019). "Previous studies have shown an indirect regulation of FGF21 on vasculopathies, including atherosclerosis and hypertension, by acting on adipocytes, hepatocytes and renal cells." (PMID 31511499, 2019). "Recent studies have also prompted a possible role of FGF21 in atherosclerosis which in turn is highly related to psoriasis." (PMID 31847236, 2019). "This is in line with studies on Wistar rats showing that FGF21 increases energy expenditure and dramatically improves atherosclerosis conditions by decreasing LDL levels and increasing HDL." (PMID 29554135, 2018). "Taken together, these results show that FGF21 alleviated the progression of atherosclerosis by suppressing Fas-mediated apoptosis in apoE−/− mice." (PMID 30157856, 2018). "Despite intensive study of the metabolic functions of FGF21, its important role in atherosclerosis needs further exploration." (PMID 30157856, 2018). "FGF21 suppressed the development of atherosclerosis, and the administration of FGF21 ameliorated Fas-mediated apoptosis in apoE−/− mice." (PMID 30157856, 2018). "The research proposes that in the cardiovascular system, FGF21 acts as an endogenous protective factor to improve endothelial function during the early stages of atherosclerosis, which is consistent with our results." (PMID 30157856, 2018). "FGF21 deficiency in ApoE KO mice results in severe atherogenic phenotypes, but administering FGF21 to these ApoE KO mice ameliorates atherosclerosis." (PMID 29738435, 2018). "Dramatically increased FGF21 levels have been reported in atherosclerosis patients in some clinical studies." (PMID 30157856, 2018). "FGF21 protects against apoptosis in HUVECs by suppressing the expression of Fas; furthermore, FGF21 alleviated atherosclerosis by ameliorating Fas-mediated apoptosis in apoE−/− mice." (PMID 30157856, 2018). "Our work provides new insight into an additional mechanism by which FGF21 can prevent atherosclerosis." (PMID 30157856, 2018). "The role of FGF21 in atherosclerosis was studied by evaluating its function in apolipoprotein E double knockout (apoE−/−) mice." (PMID 30157856, 2018). "Since FGF21 plays an important role in the regulation of lipid metabolism, the effect of FGF21 in atherosclerosis is of interest." (PMID 27247947, 2016). "Strong evidence demonstrated that FGF-21 dramatically improved the condition of atherosclerosis in Wistar rats by decreasing serum LDL levels and increasing serum HDL levels." (PMID 27247947, 2016). "This significant correlation between FGF21 and sex hormone in our study group arises a need of new studies to explain the potential role of FGF21 in atherosclerosis pathogenesis." (PMID 25850006, 2015). "Elevated mRNA expression of FGF21 was found in rat cardiac micro-vascular endothelial cells (CMECs) cultured in atherosclerosis-like conditions." (PMID 25850006, 2015).
atherosclerosis (continued). "In this study, we evaluated the association of serum FGF21 with intima-media thickness (IMT) and subclinical atherosclerosis in type 2 diabetic patients." (PMID 26047614, 2015). "Elevated serum FGF21 was found to be an independent impact factor for subclinical atherosclerosis in the full regression model, in which all relevant confounding variables were entered for both men and women (P = 0.014 and P = 0.029, respectively)." (PMID 26047614, 2015). "Evidence for the modulation of cardiovascular function exists in the context of pathological states, such as hypertension, atherosclerosis, and ischemia/reperfusion injury, for several of these batokines (FGF21, neuregulin 4, 12,13-diHOME, and BAT-derived microRNAs)." (PMID 40868154, 2025). "Collectively, these findings suggest that FGF21 may mediate some of the beneficial effects of exercise on atherosclerosis, particularly through the PI3K/AKT signaling pathway and anti-apoptotic mechanisms." (PMID 40861271, 2025). "Additionally, markers of neurodegeneration (τ protein and amyloid β-1-40), some vascular inflammation (FGF-23 and FGF-21), and atherosclerosis (LOX-1) demonstrated correlational relationships with MCP-1." (PMID 40904362, 2025). "FGF21 has been shown to exert protective effects against atherosclerosis." (PMID 40765997, 2025). "FGF21 tended to increase in patients with MASLD + atherosclerosis, and fetuin-A was correlated with CIMT alterations, suggesting that the combination of these markers could guide us to suspect early endothelial alterations in patients with MASLD." (PMID 40299570, 2025). "On the other hand, FGF21 therapy reduces the initiation and progression of atherosclerosis." (PMID 39108652, 2024). "Fibroblast growth factor 21 (FGF21), a member of the endocrine subfamily, is produced in the liver and is a 210-amino acid polypeptide that plays a crucial role in atherosclerosis, blood sugar regulation, and lipid metabolism (Jin, Xia & Han, 2021; Szczepańska & Gietka-Czernel, 2022)." (PMID 39687000, 2024). "Therefore, it is suggested that BaP can initiate atherosclerosis, and co-exposure with an atherogenic diet exacerbates the severity of lesions and consequently increases FGF21 expression." (PMID 39108652, 2024). "Notably, endogenous FGF21 expression significantly increases in atherosclerosis disease, so this increase is a compensatory response to aortic damage induced by BaP and AtD." (PMID 39108652, 2024). "The role of FGF21 in the development of atherosclerosis and whether FGF21 could serve as a reliable marker needs to be studied further." (PMID 38333506, 2024). "FGF21 may target the vascular system, protecting against atherosclerosis by inducing adiponectin to inhibit neointima formation and inflammation and suppressing hepatic cholesterol synthesis to reduce hypercholesterolemia." (PMID 39687000, 2024). "The role of FGF21 in the development of atherosclerosis and whether FGF21 could serve as a reliable marker need to be studied further." (PMID 38333506, 2024). "The protective effect of FGF21 against atherosclerosis has been proven in many preclinical trials." (PMID 36594101, 2023). "FGF21 can protect against atherosclerosis by modulating various proatherogenic cellular events." (PMID 36594101, 2023). "In addition, one in vivo study reported that FGF21 inhibits the nuclear factor kappa light chain enhancer of the activated B-cell (NF-κappaB) pathway in endothelial cells to improve atherosclerosis." (PMID 36594101, 2023). "This implies that FGF21 can be used as a biomarker of atherosclerosis." (PMID 37576954, 2023). "Moreover, studies have also shown that increasing the expression of FGF21 can ameliorate atherosclerosis." (PMID 37576954, 2023). "FGF21 has been reported to attenuate the progression of atherosclerosis, but its impact on EPCs under high oxidative stress conditions remains unclear." (PMID 35307922, 2022).